ELOVL5 (ELOVL fatty acid elongase 5)
Diseases named in the same sentence as ELOVL5 in open-access papers (continued):
Sharing a sentence is not in itself a finding about the gene and the disease.
breast carcinoma (continued). "Moreover, we cannot exclude that Elovl5 interacts with a peculiar oncogenic pathway according to the breast cancer subtype and modifies the tumor cell secretome which might create a distinct microenvironment for tumor growth and metastasis." (PMID 36056008, 2022). "Therefore, the correlation between a low expression of Elovl5 and a worse prognosis in patients with ER+ breast cancers could be explained by the fact that metastasis is promoted by Elovl5 silencing." (PMID 36056008, 2022). "Furthermore, we demonstrated an increase in TGFβ-R1 and TGFβ-R2 expression at the plasma membrane by flow cytometry analysis of breast cancer cells with suppressed Elovl5 expression while stable overexpression of Elovl5 reduced their exposure at the plasma membrane." (PMID 36056008, 2022). "The loss of Elovl5 expression did not trigger cell death but induced a cell cycle arrest in G0-G1 phase supporting the inhibition of proliferation in Elovl5-depleted breast cancer cells." (PMID 36056008, 2022). "Contrary to the results presented above, a study related the low expression of ELOVL5 and insulin-like growth factor binding protein 6 (IGFBP6) with pronounced metastasis in breast cancer." (PMID 36970499, 2023). "Inhibition of the ELOVL5 and IGFBP6 genes in breast cancer cells results in the increased expression of matrix metalloproteinase 1 and reduction of intercellular contacts." (PMID 36970499, 2023). "In this study, we focused on the role of ELOVL5 and IGFBP6 genes in the metabolism of LC-PUFAs in breast cancer cells." (PMID 36714261, 2023). "Previously we have shown that low expression of ELOVL5 and IGFBP6 genes in breast cancer tissue corresponded to poor prognosis." (PMID 36714261, 2023). "We showed that the breast cancer cells (MCF-7 and 4T1) with depletion of Elovl5 expression increased their content of intracellular LD (green dots in the cells) detected by fluorescence microscopy using Bodipy 493/503 or Nile red staining." (PMID 36056008, 2022). "Altogether, we showed that Elovl5 is involved in metastasis through lipid droplets-regulated TGF-β receptor expression and is a predictive biomarker of metastatic ER+ breast cancer." (PMID 36056008, 2022). "Mammary tumor tissues from Elovl5−/− mice also harbored higher FA and TAG content compared to mammary tumor tissues from Elovl5+/+ mice." (PMID 36056008, 2022). "Thus, for the breast cancer patients with low expression of IGFBP6 and ELOVL5 genes in cancer tissue the addition of PUFAs to the chemotherapy regimen can be potentially beneficial and should be tested in more clinically relevant settings." (PMID 36714261, 2023). "The analysis of Elovl5 mRNA levels in the METABRIC dataset showed that the expression of Elovl5 mRNA is downregulated in breast cancer tissues (n = 957 samples) compared to non-matched normal breast tissues (n = 144 samples)." (PMID 36056008, 2022). "A significant downregulation of Elovl5 expression was observed in patients with metastatic ER+ breast cancers (N1) compared to non-metastatic ER+ breast cancers (N0)." (PMID 36056008, 2022). "We demonstrated an increase in the expression of TGF-β isoforms and receptors in breast cancer cells lacking Elovl5 expression." (PMID 36056008, 2022). "However, the breast cancer aggressiveness is not dependent on the cancer cell proliferation since low expression of Elovl5 inhibited proliferation." (PMID 36056008, 2022). "To further investigate the functions of LD in Elovl5-dependent effects, we first analyzed levels of TGF-β receptors at the plasma membrane of breast cancer cells lacking Elovl5 expression and exposed to DGAT inhibitors." (PMID 36056008, 2022).
Ataxia (12 papers, 2017 to 2025). Ataxia refers to impaired coordination of voluntary muscle movement. "Heterozygous ELOVL5 variants have been associated with spinocerebellar ataxia 38 a disorder characterized by adult onset progressive ataxia, dysarthria, and nystagmus." (PMID 40590574, 2025). "SCA38, another spinocerebellar ataxia, is caused by mutations in ELOVL5, a gene encoding another elongase." (PMID 34689836, 2021). "Mutations of ELOVL5 or ELOVL4 cause spinocerebellar ataxia 38 and 34, respectively with common neurological symptoms which might be explained by the regional expression similarity between the two enzymes." (PMID 33994961, 2021). "Mutations in very long chain fatty acid elongase 4 and 5 (Elovl4 and ElovL5) are reported to cause spinocerebellar ataxia and accumulation of the branched-chain acid fatty acid was reported to be associated with Refsum disease caused by mutations in Phytanic acid alpha-oxidation (in AOA gene panel)." (PMID 33255407, 2020). "Indeed, the main symptoms of SCA38 patients with a mutation of ELOVL5 are ataxia and olfactory deficit." (PMID 29163054, 2017). "In contrast, Elovl5-deficient mice are born healthy and fertile but develop a SCA38-like phenotype with progressive ataxia, hyposmia and Purkinje cell loss." (PMID 37199746, 2023). "Here we focused on the ELOVL4 p.W246G variant as this is associated with a pure cerebellar ataxia (SCA34) and was previously noted to be located close to ELOVL5 p.G230V in SCA38." (PMID 37199746, 2023). "Missense mutations of ELOVL5 cause the spinocerebellar ataxia type 38 (SCA38), a recently discovered rare form of ataxia characterized by ataxia, hyposmia, peripheral neuropathy and cerebellar atrophy." (PMID 35933444, 2022). "This work supports that ELF2 gene regulates the expression of ATXN2 and ELOVL5 genes, and defines new molecular links in the pathophysiology of cerebellar ataxias." (PMID 29628936, 2018). "The final part of our study creates a convergent framework for the elongase-mediated spinocerebellar ataxias SCA38 (by ELOVL5 p.G230V) and SCA34 (by ELOVL4 p.W246G), demonstrating by direct structural comparison that ELOVL5 G230V and ELOVL4 W246G are position-equivalent pathogenic missense variants." (PMID 37199746, 2023). "The motor impairment observed in Elovl5−/− mice is reminiscent of the initial stages of ataxia, especially in slowly progressing forms observed in spino-cerebellar ataxia (SCA) patients, in which instability can be revealed by tandem gait while regular walking is not affected." (PMID 29163054, 2017). "Furthermore, the ELOVL5-/- mice develop ataxia and motor impairment during the balance beam test." (PMID 29628936, 2018). "The eventual phenotypic convergence between SCA38 individuals and Elovl5 KO mice, both of which develop late-onset ataxia and hyposmia, suggests that in SCA38 there must be < 50% functional ELOVL5, compatible with a dominant negative effect." (PMID 37199746, 2023).
prostate carcinoma (12 papers, 2010 to 2025). A carcinoma that arises from epithelial cells of the prostate gland. "Upon depletion of ELOVL5 in prostate cancer cells, the cells exhibited morphological and functional changes in the mitochondria, resulting in the excess generation of ROS to kill the cells." (PMID 36970499, 2023). "The expression of particular elongases (e.g. ELOVL2 in glioma or ELOVL5 in prostate cancer) supports cell growth, tumor initiation and metastasis." (PMID 36857618, 2023). "In prostate cancer cells, ELOVL5 expression was induced by androgen, and increased expression of ELOVL5 in prostate cancer was demonstrated in cultured cells, xenografts, and clinical tumors of prostate cancer." (PMID 36970499, 2023). "A previous publication reported a mitochondrial dysfunction of Elovl5-silenced prostate cancer cells affecting their proliferation." (PMID 36056008, 2022). "In this study, we identified the fatty acid elongation enzyme ELOVL5 as an important player in regulating the enzalutamide resistance of prostate cancer." (PMID 34439125, 2021). "A most recent study showed that ELOVL5 is a critical and targetable fatty acid elongase in prostate cancer metastasis and its expression can be regulated by androgen receptor." (PMID 34439125, 2021). "ELOVL5 has been shown to be markedly upregulated in prostate carcinoma cells and its inhibition has been detrimental to prostate cancer cell survival." (PMID 34206240, 2021). "ELOVL5-mediated PUFA elongation enhances the lipid raft-associated AKT-mTOR signaling activation, which is critical in enzalutamide resistance of prostate cancer." (PMID 34439125, 2021). "Very little is known about its possible association with cancer, apart from a study reporting down-regulation of ELOVL5 in prostate cancer tissue." (PMID 26672768, 2016). "A prostate cancer study showed that depletion of ELOVL5 altered mitochondrial morphology and function, leading to reactive oxygen species production, and that supplementation of ELOVL5 direct products reversed oxidative stress." (PMID 38814177, 2024). "Indeed, the depletion of Elovl5 expression in prostate cancer cells led to inhibition of cell proliferation and metastasis." (PMID 36056008, 2022). "Finally, more clinical samples are needed to test the ELOVL5 effects on the enzalutamide resistance and NE lineage switch of prostate cancer." (PMID 34439125, 2021). "Indeed, recent work has shown that ELOVL5 is significantly upregulated within prostate cancer and depletion of the elongase lead to the generation of reactive oxidative lipid species and hindered cancer cell growth and proliferation." (PMID 34421820, 2021). "Although there is still no ELOVL5 inhibitor available, our study may strongly suggest ELOVL5 as a novel target for treating the enzalutamide-resistant NE-like prostate cancer." (PMID 34439125, 2021). "There is one study where in the human prostate cancer cell line (LNCaP) with the knockdown of ELOVL2, ELOVL5, or ELOVL7, no compensatory increases in the expression of the other ELOVLs were observed in the cancer cell line, and no normal cell line was analyzed." (PMID 38139442, 2023).
Hepatic steatosis (11 papers, 2013 to 2025). Steatosis is a term used to denote lipid accumulation within hepatocytes. "At the same time, SREBP-1 is the master regulator of de novo fatty acid biosynthesis and implicated in hepatic steatosis through upregulation of expression of many lipogenic genes, including Scd1 and Elovl5, leading to elevated plasma and liver TC levels." (PMID 29593532, 2018). "Ablation of Elovl5 revealed a relationship between AA and DHA deficiency in liver and upregulation of lipogenesis via an SREBP-1c-dependent pathway that eventually caused hepatic steatosis in the Elovl5−/− mice." (PMID 24489111, 2014). "Perturbations that limit long-chain PUFA supply can derepress SREBP-1c, favor de novo lipogenesis, and promote steatosis; for example, ELOVL5 deletion induces fatty liver in mice." (PMID 41515175, 2025). "We observed repression of elongases V (ELOVL5) that in turn regulates sterol regulatory element binding protein 1c (SREBF1) to induce hepatic steatosis." (PMID 25470483, 2014). "Also, previous study using mice models revealed that a reduced ELOVL5 activity can lead to hepatic steatosis, and endogenously synthesized PUFAs are critical regulators of fatty acid synthesis." (PMID 28615065, 2017).
glaucoma (6 papers, 2012 to 2022). Increased pressure in the eyeball due to obstruction of the outflow of aqueous humor. "The Normal Tension Glaucoma Genetics Study Group of the Japan Glaucoma Society reported ELOVL5 as a new susceptibility gene for human NTG." (PMID 24040232, 2013). "However, genome-wide studies identified single nucleotide polymorphisms (SNPs) in the ELOVL5 gene that contributed to the development of primary open-angle glaucoma (POAG) including late-onset normal tension glaucoma in Japanese populations." (PMID 30291282, 2018). "Other risk factors for glaucoma include age, family history of glaucoma, diabetes mellitus, and genes related to lipid metabolism, such as ABCA1 and ELOVL5." (PMID 36012964, 2022). "The aim of the present study was to assess the potential associations of polymorphisms in the candidate genes SRBD1, ELOVL5, and ADAMTS10, with the development of canine glaucoma." (PMID 24040232, 2013). "In this study, we investigated the association between polymorphisms of the glaucoma candidate genes, SRBD1, ELOVL5, and ADAMTS10, and glaucoma in Shiba-Inus and Shih-Tzus." (PMID 24040232, 2013). "In this study, to verify recent genetic findings, we investigated the association between glaucoma in Shiba-Inu and Shih-Tzu dogs and polymorphisms of glaucoma candidate genes, SRBD1, ELOVL5 and ADAMTS10, using direct sequencing." (PMID 24040232, 2013). "In 2010, the Writing Committee for the NTG Genetic Study Group of the Japan Glaucoma Society identified SNPs of SRBD1 (OR 2.80, p = 2.5 × 10−9) and ELOVL5 (OR 1.69, p = 4.1 × 10−6) as being associated with NTG in a cohort of 305 Japanese NTG patients and 355 controls." (PMID 33396423, 2020).
Obesity (6 papers, 2016 to 2023). Accumulation of substantial excess body fat. "This shows that in women, obesity and overweight are associated with a decreased expression of ELOVL5 and ELOVL6 in GBM tumors, whereas in men, the expression of these elongases is increased." (PMID 36291290, 2022). "We also investigated ELOVL5 expression in human liver cells and in tissues from mice with induced obesity-related diabetes." (PMID 30291282, 2018). "Since, members of Elovl family contributes to obesity-induced insulin resistance, inhibition of Elovl5 might be beneficial in this model." (PMID 36709356, 2023). "Moreover, ELOVL5 expression was increased in cellular and mouse models of induced obesity-related diabetes." (PMID 30291282, 2018). "The expression of elongases in the liver, particularly ELOVL5 and ELOVL6, is higher under the influence of a fatty diet and obesity, as shown by experiments on mice." (PMID 36291290, 2022). "We discovered that the expression levels of ELOVL3, ELOVL5 and ELOVL6 increased similarly to estimated elongase activity (P<0.05), while the mRNA expression level of ELOVL1 decreased during the first year after obesity surgery (P=6 × 10−5)." (PMID 28869586, 2017).
Spinocerebellar ataxia 38 (4 papers, 2018 to 2023). "Spinocerebellar ataxia 38 (SCA 38) is an autosomal dominant disorder caused by conventional mutations in the ELOVL5 gene which encodes an enzyme involved in the synthesis of very long fatty acids, with a specific expression in cerebellar Purkinje cells." (PMID 34410614, 2022). "Furthermore, ELOVL5 is highly expressed in the central nervous system and mutations in the gene were found to be the cause of spinocerebellar ataxia type 38 (SCA38), a rare autosomal neurological disease characterized by gait abnormality, dysarthria, dysphagia, hyposmia, and peripheral neuropathy." (PMID 37663250, 2023).
Cerebellar atrophy (3 papers, 2017 to 2022). Cerebellar atrophy is defined as a cerebellum with initially normal structures, in a posterior fossa with normal size, which displays enlarged fissures (interfolial spaces) in comparison to the foliae secondary to loss of tissue. "Two different missense mutations in ELOVL5 (c.214C > G, p.Leu72Val and c.689G > T, p.Gly230Val) cause SCA38, which is characterized by gait ataxia, dysarthria, abnormal eye movements, and cerebellar atrophy with onset in the third or fourth decade." (PMID 31616255, 2019). "Two different mutations in ELOVL5 cause spinocerebellar ataxia 38 (SCA38) in humans, which is characterized by gait ataxia, nystagmus, anosmia, and cerebellar atrophy." (PMID 31616255, 2019). "The motor improvement induced by the complete diet in Elovl5-/- mice is not paralleled by an amelioration of the cerebellar atrophy, as measured by PC layer length and white matter area." (PMID 35933444, 2022).
diabetes (3 papers, 2017 to 2022). "The ELOVL5 expression, compared to ELOVL6, is not altered by SREBP-1c, glucose, or diabetes." (PMID 36291290, 2022).
glioma (3 papers, 2022 to 2024). A benign or malignant brain and spinal cord tumor that arises from glial cells (astrocytes, oligodendrocytes, ependymal cells). "However, GEPIA and Pathology Atlas do not show that a higher ELOVL5 expression is associated with a worse or better prognosis in patients with GBM or glioma." (PMID 36291290, 2022). "The enzymes required for essential fatty acid metabolism, fatty acid elongase 5 (ELOVL5), fatty acid desaturase 1 (FADS1) and fatty acid desaturase 2 (FADS2) are upregulated in low-grade glioma." (PMID 39251875, 2024).
Insulin resistance (3 papers, 2013 to 2023). Increased resistance towards insulin, that is, diminished effectiveness of insulin in reducing blood glucose levels. "We also measured ELOVL5 mRNA and protein levels in SK-Hep I cells treated with palmitate to induce insulin resistance." (PMID 30291282, 2018). "Similarly, our studies in cellular and mouse models showed that ELOVL5 levels were significantly upregulated in ob/ob mice and in a human liver cell line inducing insulin resistance and inflammation." (PMID 30291282, 2018).
steatosis (3 papers, 2014 to 2025). Increased lipid within the cytoplasm of cells. "Recently, Moon and coworkers showed that Elovl5 ablation and reduced levels of PUFA lead to steatosis by impaired suppression of SREBP-1c." (PMID 24489111, 2014). "Collectively, our previous study and current data indicate the development of severe steatosis was closely related to the genes involved in lipid synthesis, packaging, secretion, transportation, deposition or metabolism, including FADS, ELOVL1, ELOVL5, and ACAT2." (PMID 32054153, 2020).
atherosclerosis (2 papers, 2025 to 2026). A disease characterized by the build-up of fatty material and calcium deposition in the arterial wall resulting in partial or complete occlusion of the arterial lumen. "It reveals the association of ELOVL5 and ALOX5 with macrophage phenotypes, demonstrating their potential in regulating atherosclerosis-related inflammation." (PMID 41959723, 2026). "We show in an atherosclerosis mouse model that a combined Lpcat3/Elovl5 deletion in macrophages results in higher necrotic core area, a phenomenon linked to heightened macrophage sensitivity to cytotoxic oxysterols such as 7-ketocholesterol (7-KC)." (PMID 40345182, 2025).
atopic eczema (2 papers, 2013 to 2019). A common chronic pruritic inflammatory skin disease with a strong genetic component. "This study suggests that lower mRNA-expressions of FADS2 and ELOVL5 are associated with higher risk of atopic eczema in young children." (PMID 24167612, 2013). "This is the first study to confirm that FADS2 and ELOVL5 mRNA-expression is significantly lower in the peripheral blood of young children with atopic eczema." (PMID 24167612, 2013). "Furthermore, children with atopic eczema had lower ELOVL5 mRNA levels in their blood when compared to healthy controls." (PMID 31244960, 2019).
colon adenocarcinoma (2 papers, 2017 to 2023). "Validation of these regions in the TCGA colon adenocarcinoma data identified a signature of 4 genes; ELOVL5, FAM127B, MTERF1 and ZNF606, which are downregulated in hypermethylated tumors." (PMID 28931069, 2017).
colon cancer (2 papers, 2021 to 2022). "However, we found a strong upregulation of ELOVL5 (corresponding with increased calculated ELOVL5/2 activity) in colon tumors." (PMID 34206240, 2021). "In addition, two FA elongases, ELOVL5 and 6, were also downregulated in AhR KO colon cancer cells." (PMID 36077780, 2022).
Hepatitis (2 papers, 2018 to 2025). Inflammation of the liver. "The effects of the ER stress on the differentially expressed proteins Elovl5 and Ptbp3 during hepatitis were further demonstrated." (PMID 41209571, 2025). "The decreased levels of PUFA in hepatitis patients in comparison to controls, which specifies the reduced activities of ELOVL2, ELOVL4 and ELOVL5 enzymes." (PMID 29506525, 2018).
hepatocellular carcinoma (2 papers, 2018 to 2020). A malignant tumor that arises from hepatocytes. "ELOVL5 knockdown experiments also significantly decreased the majority of the elongation capacity of 18-carbon PUFAs in HepG2 hepatoma cells, despite the fact that these cells also express ELOVL2." (PMID 30293059, 2018).